INS (insulin)
Diseases named in the same sentence as INS in open-access papers (continued):
Sharing a sentence is not in itself a finding about the gene and the disease.
Insulin resistance (continued). "The findings of this randomized controlled trial demonstrated that, in comparison with the placebo population, participants who took L. casei supplementation for eight weeks exhibited enhancements in their preprandial blood glucose concentration, insulin concentration, and insulin resistance." (PMID 38931292, 2024). "Nucleotide-binding oligomerization domain 1 (NOD1) or NOD-like Receptor pyrin domain containing 3 (NLRP3) activation promote metabolic inflammation and insulin resistance while NOD2 activation improves insulin sensitivity and glucose homeostasis during obesity." (PMID 41853552, 2024). "The insulin dose measures insulin resistance in children and adolescents." (PMID 38397939, 2024). "A subsequent study found that the specific deletion of GLUT4 in adipocytes significantly increased RBP4 levels, which induced the expression of gluconeogenic enzymes in the liver and impaired insulin signalling in the muscle, thereby inducing insulin resistance." (PMID 39698033, 2024). "However, in states of insulin resistance, the muscle’s ability to uptake glucose in response to insulin is significantly reduced, leading to persistently high blood glucose levels and potentially resulting in metabolic disorders such as type 2 diabetes." (PMID 38611884, 2024). "Many factors may explain this sexual dimorphism but differences between men and women in insulin action could be of great importance because insulin resistance is paramount for the development of T2DM." (PMID 38491191, 2024). "This process can lead to decreased insulin secretion by the pancreas, increased insulin resistance, and liver dysfunction, which contributes to a decrease in glucose uptake by the muscles and an increase in gluconeogenesis, ultimately resulting in the development of GDM." (PMID 39666683, 2024). "According to previous research, androgen may contribute to insulin resistance and alter how insulin functions in the target tissue in PCOS." (PMID 38276279, 2024). "As the main tissue target for insulin action and a major contributor to insulin resistance, lean body mass (primarily skeletal muscle) may play a beneficial role for reducing risk of T2DM." (PMID 38632599, 2024). "Additionally, an animal experiment has indicated that high Se levels can induce hepatic insulin resistance by either promoting lipolysis-induced damage from reactive oxygen species (ROS) or suppressing insulin-stimulated ROS signaling." (PMID 38459526, 2024). "Thus, the site of insulin resistance in diet-induced insulin-resistant conditions should be determined." (PMID 39195275, 2024). "Our participants were all healthy, lean, insulin-sensitive men, and whether the effect would be the same in people with insulin resistance is unknown." (PMID 38324259, 2024). "The current results suggested that selenium supplementation may be an effective treatment for reducing insulin resistance as it decreases serum insulin levels and HOMA-IR, but the effectiveness of Se supplementation on fast plasma glucose, levels was unclear." (PMID 37880477, 2024). "Furthermore, these bioactives normalize insulin secretion and counteract insulin resistance conditions." (PMID 39062550, 2024). "Third, obesity not only induces peripheral insulin resistance but may also trigger brain insulin resistance, marked by impaired insulin-induced long-term inhibition and reduced insulin signaling in the brain." (PMID 39634656, 2024). "In practice, measuring for high blood sugars, fasting-insulin levels, and tests of insulin resistance, like HOMA IR (homeostasis model assessment), Triglyceride glucose–body mass index (TyG–BMI), Leptin, Amylin, and Heme oxygenase (HO-1) levels, are also useful." (PMID 39518747, 2024). "Increased lean mass was associated with increased fasting insulin and insulin resistance in females but not in males." (PMID 38173399, 2024).
Insulin resistance (continued). "Insulin resistance, a prominent pathogenic mechanism in T2DM, results from abnormalities in insulin signaling pathways at various levels, including the insulin receptor, insulin receptor substrate phosphorylation, and the postreceptor signaling pathways, leading to inadequate insulin responsiveness." (PMID 39479660, 2024). "Moreover, obese-DS exhibited a prominent atherogenic lipid profile and higher insulin resistance indices (fasting insulin and HOMA-IR values) compared to matched obese-control." (PMID 37930396, 2024). "Dietary fats and sugars are known to increase systemic inflammation and may contribute to the higher levels of insulin and insulin resistance observed in this population." (PMID 38463689, 2024). "This observational study examined the effects of cumulative sedentary time (ST), light PA (LPA), and moderate to vigorous (MVPA) on glucose, insulin, and homeostatic model assessment for insulin resistance (HOMA-IR) in 11-year-old children followed up for 13 years until young adulthood." (PMID 38441224, 2024). "Determining the cut-off values for visceral adipose tissue and the measured parameters in the male cohort revealed that it was 231 cm2 for a fasting insulin concentration of ≥10 mU/mL, 168 cm2 for the presence of insulin resistance, and 194 cm2 for the presence of hypertriglyceridemia." (PMID 38732548, 2024). "↑ BW (decreased in T1DM model); ↓ BW, plasma insulin levels, insulin resistance (increased in T2DM model) and ↓ s-glu, HbA1c, albuminuria, s-creat, oxidative stress, HO-1, NF-κB, mesangial expansion, ECM, fibronectin, collagen 4-α1, VEGF, endothelin-1, and TGF-β1." (PMID 39652245, 2024). "It has been observed, indeed, that LPL activity in skeletal muscle negatively correlates with plasma insulin levels and it has been suggested that it could be lowered by insulin resistance." (PMID 38674801, 2024). "In addition, exosomes derived from ATMφs in obese mice induced pancreatic β-cell insulin secretion and insulin resistance when injected into lean mice." (PMID 39063184, 2024). "Moreover, in the groups treated with both LC and GB, the FBG, insulin, and insulin resistance indices are significantly lower (p < 0.05) than those in the HCD group by approximately 31.44%, 29.5%, and 19.86%, respectively." (PMID 38727268, 2024). "Insulin resistance (IR) is one of the major pathophysiological causes of diabetes which occurs due to nonfunctioning of insulin signaling pathway, resulting in the gradual incidence of insulin deficiency." (PMID 39490585, 2024). "Blood samples were collected before and after training, and subjects were tested for changes in clinical parameters, insulin resistance indices [fasting insulin, homeostatic model assessment insulin resistance (HOMA-IR)], MMP-2 and -9, and hydroxyproline, and muscle strength (12-RM), respectively." (PMID 39029066, 2024). "Our data demonstrated other metabolic markers, such as fasting blood sugar, insulin levels, and the homeostatic model assessment of insulin resistance (HOMA-IR) index, illustrating a significant impairment of glucose homeostasis and insulin resistance in CCl4-administered mice." (PMID 39654627, 2024). "This hypoglycemia may be due to DM1-specific insulin resistance, hyperinsulinemia, and an enhanced insulin response to carbohydrates." (PMID 39274465, 2024). "Similarly, EVs obtained from ATMs of lean mice, when given to obese mice, can improve glucose tolerance and insulin sensitivity, while injections of exosomes isolated from ATMs of obese mice induce glucose intolerance and insulin resistance in lean mice." (PMID 39735643, 2024). "The levels of fasting insulin and the homeostasis model assessment of the insulin resistance index were significantly increased in the PCOS-like rats compared to the control group (p < 0.0001), indicating that insulin resistance was observed in this PCOS animal model." (PMID 39201391, 2024).
Insulin resistance (continued). "Importantly, local insulin sensitization from increased FAHFA concentrations in adipose tissue itself can reduce systemic insulin resistance, partly mediated by reduced serum insulin." (PMID 38816388, 2024). "Anthropometric indices, lipid profile, fasting blood glucose, insulin, Homeostatic Model Assessment for Insulin Resistance, aspartate transaminase, alanine aminotransferase, high sensitivity C-reactive protein and malondialdehyde were measured at baseline and at the end of the study." (PMID 39086859, 2024). "Likewise, prolonged exposure in utero to excessive glucocorticoids (GCs) levels deteriorates the offspring glucose/insulin metabolic profiles and outcomes in insulin resistance (IR)." (PMID 39000130, 2024). "Some evidence has shown that STING-IRF3 may interact with components of the insulin signalling pathway and regulate insulin resistance under conditions of obesity." (PMID 38164186, 2024). "One such recent study reported hypermethylation and significant correlation of the expression of the GFPT2 gene with enrichment in the insulin resistance and insulin signalling pathways, suggesting that this gene is a suitable candidate biomarker for metabolic syndrome." (PMID 39415250, 2024). "In a cross-sectional study in children aged 11–15 years (42% female), low IGFBP-1 was an independent marker of insulin resistance (determined by fasting insulin and response to intravenous glucose) and was better than elevated triglycerides and decreased HDL and adiponectin levels." (PMID 39595651, 2024). "Moreover, the levels of leptin and insulin, which are insulin resistance indicators, significantly increased in the obese group but were significantly decreased in the PGA-K-treated group." (PMID 38542720, 2024). "However, insulin resistance disrupts this finely tuned process and manifests when cells exhibit diminished responsiveness to insulin’s regulatory effects." (PMID 39408856, 2024). "Recently, brain insulin resistance has been found to play a role in normal memory processes, and insulin irregularities may contribute to cognitive and brain changes associated with AD." (PMID 38167548, 2024). "In patients with GDM, glucose homeostasis and insulin resistance parameters were higher than in patients from the control group (fasting glucose level (p < 0.0001), insulin level (p = 0.005), C peptide level (p = 0.01), HbA1c (p < 0.0001), IR HOMA (p = 0.0004))." (PMID 39064123, 2024). "In T2DM, the chronic hypersecretion of insulin as brought about by cellular insulin resistance may lead to beta-cell exhaustion and impaired insulin release, causing impaired glucose tolerance." (PMID 38474713, 2024). "It is possible that these findings might have been affected by the fact that metformin is more likely to be used in patients with insulin resistance and that glinide is more likely to be used in patients with impaired insulin secretion." (PMID 38839813, 2024). "Moreover, obesity-linked insulin resistance and hyperglycemia increase unbound insulin growth factor-1 (IGF-1) protein in the blood, activating insulin and IGF-1 receptor signaling pathways that ultimately promote tumor growth." (PMID 39410536, 2024). "Compared with isocaloric balanced diets (BDs), HPDs significantly reduced fasting insulin (−2.69 μIU/mL, 95% CI [−3.81, −1.57], P < 0.0001, I2 = 46%) and homoeostatic model assessment for insulin resistance (HOMA-IR−0.41, 95% CI [−0.80, −0.02], P = 0.04, I2 = 94%) in women with PCOS." (PMID 38424054, 2024). "Another study suggested that the increased proteolysis observed in obesity and insulin resistance may be attributed to the compromised anti-proteolytic function of insulin." (PMID 39007094, 2024). "Additionally, there was a marked reduction in lipid profiles, including TG, LDL-C, and HDL-C, and notable decreases in insulin, insulin resistance, BMI, TNF-alpha, and CRP levels." (PMID 38248762, 2024).
Insulin resistance (continued). "We identify several consistent changes (individual genes, proteins, and molecular pathways) occurring across all insulin-resistant kidney cell types, together with cell-line-specific changes occurring in response to insulin resistance, which are replicated in DKD biopsies." (PMID 39562547, 2024). "In addition, HFD increased plasma insulin and eWAT IL-6 levels in Apoe-null mice, both of which indicated insulin resistance." (PMID 39156133, 2024). "Importantly, insulin resistance and inflammation were still induced in the 12 h treated adipocytes: the expression of the insulin sensitive and inflammatory genes was decreased and increased, respectively." (PMID 39415617, 2024). "When insulin sensitivity is reduced, it is usually accompanied by insulin resistance." (PMID 39076779, 2024). "Six variables related to insulin sensitivity/insulin resistance and insulin secretion/beta cell function changed differently in response to weight gain between SA and WE: fasting insulin, postprandial insulin, HOMAIR, the Matsuda insulin sensitivity index, insulin AUC/glucose AUC and ISSI-2." (PMID 39152223, 2024). "ICP might indirectly affect insulin activity by influencing hormone levels, such as estrogen and progesterone, thus inducing or exacerbating insulin resistance." (PMID 39238593, 2024). "Insulin resistance, a key feature of MetS, prevents cells from efficiently using glucose for energy, leading to elevated blood sugar levels and compensatory increases in insulin production." (PMID 39429422, 2024). "Since insulin resistance is associated with hyperinsulinemia, it is also consistent with our observation of no plasma insulin induction by HFD in the Apoe/Cd36 double-null mice." (PMID 39156133, 2024). "Thus, decreased HGU and increased EGP during insulin stimulation are specific markers of hepatic insulin resistance." (PMID 38989003, 2024). "In addition, animal experiments have shown that oxidative stress can exacerbate insulin resistance by blocking insulin signaling via the activation of nuclear factor-kappa-B (NF-κB)." (PMID 39590972, 2024). "Insulin resistance is a condition where insulin-dependent glucose update by cells is impaired." (PMID 38922352, 2024). "In many studies on obesity or type 2 diabetes, a strong correlation has been observed between the clamp method and mathematical formulas based on the assessment of fasting insulin and glucose levels, such as the Homeostatic Model Assessment of Insulin Resistance (HOMA-IR)." (PMID 38792408, 2024). "Thus, while DNA methylation contributes to sexual dimorphism in gene expression and Rho activation, it does not appear to contribute to differences in gene expression related to insulin resistance or to the reduction in insulin-stimulated glucose uptake." (PMID 38032738, 2024). "It reduces liver glucose production, enhances insulin sensitivity in body tissues, decreases hyperinsulinemia by reducing insulin resistance and increases the secretion of growth/differentiation factor 15 (GDF15), which suppresses appetite and reduces caloric intake." (PMID 38665260, 2024). "Furthermore, animal studies have shown that jujube polysaccharides alleviated insulin resistance and slowed down hyperinsulinemia development by downregulating serum insulin concentrations as well as HOMA-IR and HOMA-β." (PMID 38254493, 2024). "The placenta appears to contribute to the pathogenesis of GDM as it affects insulin resistance progression, and its delivery during labor seems to improve glucose metabolism, which is reflected in the reduced demands for the insulin used to treat GDM shortly after delivery." (PMID 38339106, 2024). "Another dysmetabolic theory purports that insulin resistance may contribute to aminoacidemia by increasing the protein catabolism, which insulin typically inhibits, and/or by impairing tissue-dependent BCAA oxidative metabolism." (PMID 39347258, 2024).
Insulin resistance (continued). "Therefore, it is crucial to approach the interpretation of these results, especially concerning the insulin status and the potential beneficial role of NS in managing insulin resistance in obesity, with careful consideration." (PMID 38178093, 2024). "Besides, HOMA-IR enables the quantification of insulin resistance and β cell function based on basal glucose and insulin concentrations, making it a widely utilized surrogate marker for assessing insulin resistance in research studies." (PMID 38429794, 2024). "Impaired insulin secretion and insulin resistance are characteristic features of type 2 diabetes." (PMID 38673770, 2024). "Nevertheless, in cases of GDM, the adaptive response of the β-cells may be inadequate, resulting in insufficient insulin secretion despite elevated insulin resistance." (PMID 39683486, 2024). "Second, higher total fat mass in mid-adolescence may temporally precede higher insulin resistance by late adolescence, progressing to a bidirectional relationship between total fat mass and insulin resistance by young adulthood." (PMID 38173399, 2024). "(b) Insulin resistance, glucose intolerance, and type 2 diabetes, are exacerbated by liver dysfunction, hormonal imbalances, and conditions stemming from ineffective insulin function, including issues with blood circulation and kidney function." (PMID 39407941, 2024). "Most importantly, BBR can also increase insulin sensitivity and improve insulin resistance." (PMID 39421985, 2024). "While in the overweight (high BMI) group, insulin resistance (classic insulin resistance) with elevated fasting insulin and a high HOMA index is detected in the majority of cases, in the normal or low weight (low BMI) group, fasting insulin is not elevated and the HOMA index is below 2.0." (PMID 38337532, 2024). "In addition to the impairment of insulin secretion, ROS are major players in developing insulin resistance by rendering cells insensitive to insulin, thus hindering the insulin signaling pathway in peripheral tissues such as SKM, adipose tissue, and the liver." (PMID 38255314, 2024). "In individuals with insulin resistance, dietary fiber may enhance peripheral insulin sensitivity, possibly through short-chain fatty acids produced by the fermentation of fiber in the intestines." (PMID 39337936, 2024). "Collectively, these elements contribute to hepatic insulin resistance, elevated insulin levels (hyperinsulinemia), inflammation, oxidative stress, mitochondrial dysfunction, an imbalance in pro-inflammatory cytokines, and the progression from steatosis to fibrosis." (PMID 38248762, 2024). "Studies have confirmed that the systemic insulin resistance observed in type 2 diabetes is reflected in the inability of cells to respond appropriately to insulin signals in the brain, which is manifested by impairment in cognitive areas such as executive function, memory, and processing speed." (PMID 39452046, 2024). "MetS involves insulin resistance with high insulin concentrations, which incentivize lipogenesis, steroidogenesis, and protein production, and, as a growth factor element, incentivizes cellular production with anti-apoptotic roles, especially in hormone-independent prostate cancer cells." (PMID 38785834, 2024). "Levels of particulate matter with aerodynamic diameters ≤ 10 μm (PM10) and ≤ 2.5 μm, and nitrogen dioxide (NO2) were significantly associated with increased fasting blood glucose, Hemoglobin A1c, insulin, and homeostatic model assessment for insulin resistance (HOMA-IR) values." (PMID 39425159, 2024). "A downregulation of the insulin/IGF signaling pathway might also contribute to insulin resistance in adipose tissue and other organs that orchestrate glucose metabolism." (PMID 37934800, 2024).